MTOR (mechanistic target of rapamycin kinase)
Diseases named in the same sentence as MTOR in open-access papers (continued):
Sharing a sentence is not in itself a finding about the gene and the disease.
neuroblastoma (continued). "Furthermore, we demonstrated that only the mammalian target of rapamycin (mTOR)-independent autophagy activators could protect against proteasome impairment-induced cytotoxicity in human neuroblastoma cells." (PMID 34298888, 2021). "Furthermore, we provide evidence demonstrating that mTOR-independent autophagy activators may be protective in neuroblastoma cells and thus can be regarded as neuroprotective agents." (PMID 34298888, 2021). "Interestingly, we and others previously noticed an increased sensitivity of MYCN-dependent neuroblastoma towards mTOR inhibition, suggesting that simultaneous blockade of glycolysis and mTOR would be an option to interfere with both, metabolism and survival pathways." (PMID 32346009, 2020). "Collectively, these findings demonstrate that 4-MD engages multiple, non-redundant cell death pathways through coordinated ROS-MAPK-AMPK/mTOR/ULK1 signaling, highlighting its potential to overcome therapeutic resistance in heterogeneous neuroblastoma cells." (PMID 41827863, 2026). "According to numerous literature data, all of the metabolic pathways studied (glycolysis, glutaminolysis, fatty acid biosynthesis, and one-carbon metabolism), as well as mTOR and NMYC, are important and prospective drug targets in neuroblastoma." (PMID 41304961, 2025). "Several signaling pathways, including PI3K/AKT/mTOR, Notch, Wnt, and MAPK/ERK, are typically deregulated in neuroblastomas." (PMID 41304961, 2025). "To assess the impact of polyphenols and their combinations on the signaling in neuroblastoma cell lines, we have applied Western blot for the key components of AKT/mTOR, MAPK/ERK, and β-catenin signaling pathways that are frequently altered in neuroblastoma." (PMID 41304961, 2025). "The increased activity of the IGF1R/PI3 kinase/AKT/mTOR pathway induces proliferation, prevents apoptosis, increases motility, induces differentiation, and drives MYCN expression in neuroblastoma cells." (PMID 39001383, 2024). "Monoclonal antibodies specific for the IGF1R ligands, as well as inhibitors of PI3 kinase and mTOR, which are activated by signaling through IGF1R, are also effective in neuroblastoma models." (PMID 39001383, 2024). "Neuroblastoma cells, like rhabdomyosarcoma cells, are sensitive to the inhibition of the RAS/MAPK and IGF1R/AKT/mTOR pathways." (PMID 39001383, 2024). "Our study supported that phosphorylated mTOR, PI3K, and AKT expressions were intensely expressed in the cytoplasm of the control group in the xenograft neuroblastoma model." (PMID 37370314, 2023). "The combination of monensin and rapamycin was to reduce the growth of xenograft neuroblastoma tumor tissues, trigger apoptosis, and suppress the expression of PI3K/AKT/mTOR." (PMID 37370314, 2023). "The aim of this study was to investigate the therapeutic effects of single and combination treatments of monensin and rapamycin on PI3K/AKT/mTOR signaling pathway-mediated apoptosis and tumor growth in the SH-SY5Y human neuroblastoma cell xenograft model." (PMID 37370314, 2023). "PCNP mediates the proliferation, migration, and invasion of human neuroblastoma cells through the MAPK and the PI3K/AKT/mTOR signaling pathways." (PMID 36591491, 2022). "For example, our previous study revealed that PCNP mediated the growth of human neuroblastoma cells via MAPK and PI3K/Akt/mTOR pathways." (PMID 35813472, 2022). "In human neuroblastoma cells, relatively high activation of the PI3K/Akt/mTOR signaling pathway has been reported." (PMID 34573138, 2021). "In the current studies, we have shown that METH treatment with SH-SY5y neuroblastoma cells reduces the phosphorylation level of PI3K, Akt, and mTOR but pre-treatment with lupenone partially recovers." (PMID 32120831, 2020).
neuroblastoma (continued). "In a validation test, the mTOR pathway was activated on the protein level in MYCN-driven neuroblastomas in mice and activation of MYCN in SH-EP MYCN-ER cells resulted in high sensitivity to mTOR inhibition was observed." (PMID 32117438, 2020). "Resveratrol induces autophagy by directly inhibiting the mTOR signaling pathway in HeLa cells, and OXY activates autophagy via inhibition of PI3K/AKT/mTOR and activation of p38 MAPK signaling pathways in neuroblastoma cells." (PMID 32150901, 2020). "Our results further demonstrate alterations in the activity of numerous other signalling pathways in neuroblastoma cells after treatment with regorafenib, including the PI3K/mTOR/Akt and Fos/Jun pathways." (PMID 32457362, 2020). "mTOR was shown to phosphorylate STAT3 at Ser727, and then promote its transcriptional activity in neuroblastoma cells." (PMID 31949495, 2020). "We show that the PIM/PI3K/mTOR inhibitors IBL‐301 and IBL‐302 induced neuroblastoma cell differentiation and cell death at nanomolar concentrations." (PMID 31310053, 2019). "Our previous study has demonstrated that PCNP can mediate the growth of human neuroblastoma cells via MAPK and PI3K/Akt/mTOR pathways." (PMID 30872582, 2019). "Treatment with IBL‐202 and IBL‐301 reduced cell viability in two PDX lines and two conventional neuroblastoma cell lines, and the triple PIM/PI3K/mTOR inhibitor IBL‐301 had distinctly lower GI50." (PMID 31310053, 2019). "We used neuroblastoma patient‐derived xenografts (PDXs) and cell lines to investigate the benefit of combination therapies directed toward PIM, PI3K, and mTOR pathways." (PMID 31310053, 2019). "Signaling via the PI3K/Akt pathway in neuroblastoma regulates the phosphorylation of MYCN through GSK3b and mTOR, which makes this pathway a suitable candidate for pharmacological inhibition in order to indirectly target MYCN stability." (PMID 35582571, 2019). "Preferential sensitivity to inhibitors of PI3K/mTOR, including NVP-BEZ235, were prominently identified in a chemical-genetic screen of isogenic neuroblastoma cells with genetically modified MYCN stabilization versus wild-type MYCN expression." (PMID 35582571, 2019). "We found cell proliferation and survival signaling pathways AKT2/mTOR and MAPK were enhanced in cisplatin (CDDP)- and radiation-resistant neuroblastoma cells." (PMID 31608140, 2019). "Neuroblastoma cells, like many cancer cells, have an overactivated AKT/mTOR signaling pathway, suggesting involvement in drug- and radiation-resistance mechanisms." (PMID 31608140, 2019). "The PI3K/AKT/mTOR pathway appears to play a role in MYCN stabilization and aberrant activation of the pathway has been demonstrated in neuroblastoma." (PMID 30326621, 2018). "PCNP mediates the proliferation, migration, and invasion of human neuroblastoma cells through mitogen-activated protein kinase and PI3K/AKT/mTOR signaling pathways, implying that PCNP is a therapeutic target for patients with neuroblastoma." (PMID 29716528, 2018). "In our previous studies, we showed that in neuroblastoma cells, OA induces autophagy through activation of the Ca2+/CaMKKβ/AMPK/mTOR signalling pathway, a mechanism in accordance with that previously reported for other polyphenols." (PMID 29765503, 2018). "Phosphorylations of PI3K (Tyr458/Tyr199), AKT (Ser473), and mTOR (Ser2448) decreased in the PCNP group and increased in the sh-PCNP group, suggesting that PCNP mediates the PI3K/AKT/mTOR signaling pathway in human neuroblastoma cells." (PMID 29716528, 2018). "The New Approaches to Neuroblastoma Therapy (NANT) consortium has an ongoing phase 1 trial of SF1126, a pan-PI3K/mTOR inhibitor that is a novel RGDS-conjugated LY294002 prodrug." (PMID 30326621, 2018). "Nevertheless, PCNP knockdown promoted the growth, migration, and invasion of neuroblastoma cells via increasing phosphorylations of PI3K (Tyr458/Tyr199), AKT (Ser473), and mTOR (Ser2448)." (PMID 29716528, 2018).
neuroblastoma (continued). "In conclusion, these results indicate that ER stress is involved in neuroblastoma cell apoptosis induced by CHERP depletion; moreover, up-regulation of DR5 and inhibition of the AKT/mTOR/4E-BP1 pathway represent two separate downstream events of this process." (PMID 29113358, 2017). "We found that the levels of AKT, mTOR and 4E-BP1 phosphorylation were attenuated after CHERP depletion, which indicated that the AKT/mTOR/4E-BP1 pathway was involved in neuroblastoma cell apoptosis mediated by CHERP depletion." (PMID 29113358, 2017). "Taken together, these results show that afatinib inhibits neuroblastoma growth both in vitro and in vivo by suppressing EGFR-mediated PI3K/AKT/mTOR signaling." (PMID 27902463, 2017). "Inhibitors for the PI3K/mammalian target of rapamycin (mTOR)/AKT axis lead to increased GSK3ß activity and, thus, to increased MYCN protein degradation, inducing growth arrest and apoptosis in neuroblastoma cells both in vitro and in vivo." (PMID 28358317, 2017). "In brief, we reveal that the down-regulation of CHERP induces apoptosis in neuroblastoma cells by activating the ATF4/CHOP/DR5 signaling axis and inhibiting the AKT/mTOR signaling pathway." (PMID 29113358, 2017). "Neuroblastoma tissue was found to have significant levels of activated AKT and mTOR compared to the normal adrenal medulla." (PMID 26771642, 2016). "Encouraged by these findings, we aimed to investigate how the combination of mTOR inhibitors and MEK inhibitors would affect cell growth of NRAS mutant neuroblastoma cell lines." (PMID 26821351, 2016). "In conclusion, we show that mutant NRAS neuroblastoma can be targeted by single MEK and mTOR inhibitors or their combinations." (PMID 26821351, 2016). "Recently, Hono was reported to induce autophagy and suppress cell migration through activating the PI3K/Akt/mTOR and endoplasmic reticular stress/ERK signaling pathways in neuroblastoma cells." (PMID 27074557, 2016). "Inhibition of mTOR with rapamycin and an analog, CCI-779, decreased neuroblastoma cell proliferation, indicating a role for the PI3K/AKT/mTOR pathway in tumorigenesis." (PMID 26771642, 2016). "In the present study, we have evaluated and screened the efficacy of the NF-kB/mTOR dual inhibitor 13-197, PLK1 inhibitor BI2536 and hedgehog pathway inhibitor vismodegib alone or in combination with topotecan against neuroblastoma." (PMID 26934655, 2016). "Aberrant activation/expression of pathways/molecules including NF-kB, mTOR, hedgehog and polo-like-kinase-1 (PLK1) are correlated with poor-prognosis neuroblastoma." (PMID 26934655, 2016). "In summary, inhibition of mTOR complex alone by Everolimus reduced cell growth and induced apoptosis in NRAS mutant neuroblastoma." (PMID 26821351, 2016). "In neuroblastoma, another embryonal tumor, in which amplification of MYC family genes is correlated with poor prognosis, targeting PI3K/mTOR resulted in down-regulation of MYCN expression." (PMID 25402633, 2015). "In this context, we explored if a crosstalk between mTOR/S6K1 and HH signaling is relevant in neuroblastoma." (PMID 25134527, 2014). "Taken together, our work reveals high levels of IGF-1R/IR and Ret phosphopeptides, with associated high abundance of phosphopeptides from downstream mediators of the PI3K/Akt/mTor and Raf/MEK/ERK pathways in MYCN-amplified neuroblastoma." (PMID 24349301, 2013). "Phosphopeptides derived from proteins specific to the PI3K/Akt/mTor and the Raf/MEK/ERK pathways were significantly increased in neuroblastoma cells." (PMID 24349301, 2013). "Phosphopeptides from the transcription factor c-Myc, an end-target of both PI3K/Akt/mTor and Raf/MEK/ERK signaling were elevated in the neuroblastoma cell line as well." (PMID 24349301, 2013). "Furthermore, these combinations significantly suppressed AKT/mTOR, ERK, and β-catenin–mediated signaling pathways that are critical for neuroblastoma development." (PMID 41304961, 2025).
neuroblastoma (continued). "Some studies have further shown that BDNF/TrkB can increase neuroblastoma metastasis via the PI3K/Akt/mTOR and MAPK pathways, indicating that BDNF/TrkB and its downstream targets may be potential therapeutic targets for treating neuroblastoma metastasis." (PMID 39648800, 2024). "Even though pharmacologic mTOR inhibitors, such as rapamycin, are in clinical use in patients suffering from different cancers, including MYCN-amplified neuroblastoma, biomarkers predicting mTOR inhibitor sensitivity are largely lacking." (PMID 38197697, 2024). "Moreover, SHP2 inhibition has recently been shown to reduce MAPK and mTOR signaling via inactivation of ERK, mTORC1, and S6K in neuroblastoma cells and tumors with low NF1 expression." (PMID 38032104, 2023). "We focused our study on the hypothesis of the effects of the combination of monensin and rapamycin on apoptosis of xenograft neuroblastoma tumor cells in vivo and the role of the PI3K/AKT/mTOR pathway on this development in an advanced preclinical stage." (PMID 37370314, 2023). "The aim of this study was to investigate the therapeutic effects of single and combined monensin and rapamycin treatments on mTOR (mammalian target of rapamycin) signaling pathway-mediated apoptosis and tumor growth in an SH-SY5Y neuroblastoma cell xenograft model." (PMID 37370314, 2023). "We found that in both SCLC and neuroblastoma, cell lines with higher NE scores were more resistant to drugs that target MEK, mTOR, XIAP, LCK, HSP90, and Abl but were more sensitive to BCL inhibitors, which inhibit anti-apoptotic B-cell lymphoma-2 (Bcl-2) family of proteins." (PMID 37255415, 2023). "Trehalose, on the other hand, enhances autophagy not by mTOR inhibition and, indeed, compatible with our report in neuroblastoma cells, here it elevated autophagy following eight weeks of rotenone treatment." (PMID 36690794, 2023). "Several mTOR inhibitors have already been approved for the therapeutic treatments of different types of cancer, while in neuroblastoma new clinical trials are ongoing (NCT02337309, NCT03213678) making mTOR inhibition a very promising therapeutic avenue for MYCN-deregulated childhood cancers." (PMID 36139583, 2022). "Therefore, we combined mTOR activity, differentiation score, and MYCN status into a single score to predict the survival of neuroblastoma patients." (PMID 35490242, 2022). "Our previous study has shown that PCNP could mediate the growth of human neuroblastoma cells via mitogen-activated protein kinase (MAPK) and phosphatidylinositol 3-kinase (PI3K)/Akt/mammalian target of rapamycin (mTOR) pathways." (PMID 30872582, 2019). "The study suggests that PCNP could mediate the proliferation, migration, and invasion of human neuroblastoma cells through MAPK and PI3K/AKT/mTOR signaling pathways." (PMID 29716528, 2018). "We next wanted to see whether combining these inhibitors of the NF-κB/mTOR, hedgehog and PLK1 with topotecan resulted in a corresponding declines in expression/activation of the respective pathways/molecules in neuroblastoma cells." (PMID 26934655, 2016). "Furthermore, the survival of MYCN transgenic mice bearing neuroblastoma was improved by treatment with NVP-BEZ235, a dual PI3K/mTOR inhibitor shown to destabilize MYCN via GSK3β activation." (PMID 24391509, 2014). "The potential of NVP-BEZ235, a novel PI3K/mTOR inhibitor, as a single therapeutic agent has already been investigated in MYCN-amplified neuroblastoma, where it could be shown to exert both, an antiproliferative effect and a blockage of tumor angiogenesis." (PMID 24391739, 2013). "Specifically, our work suggests that combined inhibition of both the PI3K/Akt/mTor and Raf/MEK/ERK pathways may significantly alter neuroblastoma cell viability." (PMID 24349301, 2013). "Isolated targeting of IGF-1R/IR, Ret, PI3K, MEK, and mTor has been trialed in neuroblastoma, with or without traditional chemotherapy." (PMID 24349301, 2013).
neuroblastoma (continued). "Notably, there is an additional example were bosutinib was similarly repurposed against neuroblastoma, where it was shown capable of suppressing oncogenic activity via targeting multiple signaling pathways including Src/Abl and PI3K/AKT/mTOR, MAPK/ERK, and JAK/STAT3." (PMID 39202022, 2024). "In turn, shRNA-mediated DDX1 knockdown in neuroblastoma cells with a DDX1-MYCN coamplification resulted in reduced rapamycin sensitivity, indicating that high DDX1 expression was required for mTOR inhibitor sensitivity in the context of DDX1-MYCN coamplification." (PMID 38197697, 2024). "As we and others have previously reported, activation of the ERK1/2 and mTOR signaling pathways by NI-hADSC-CM appears to bring about the upregulated expression of proteins related to neuronal differentiation, such as neuron-specific class III β-tubulin (Tuj1) in neuroblastoma cells." (PMID 35457010, 2022). "Thus, mTOR pathway inhibitors are not specific for neuroblastoma cells and present different side effects in normal cells, limiting their potential clinical use." (PMID 35490242, 2022). "Therefore, we applied hydroxychloroquine (HCQ) for inhibiting amino acid metabolism in cisplatin-insensitive neuroblastoma cells based on the premise that HCQ inhibits terminal phase of autophagy, recycling of cellular receptors involved in nutrient uptake, as well as mTOR pathways." (PMID 32927667, 2020). "Further mechanistic studies elaborating the role of mTOR mediating signaling and autophagic flux in CDDP treated neuroblastoma cells are warranted to establish the role mechanisms regulating amino acid signaling and autophagy in drug resistance models of neuroblastoma." (PMID 32927667, 2020). "However, neuroblastoma or squamous cell carcinoma seem to be resistant to autophagy induction mediated by rapamycin, apparently because RAPTOR maintains bound to mTOR, and these cells are sensitized only when they are treated with mTOR catalytic inhibitors." (PMID 32232004, 2020). "In addition, we previously showed that increased oxidative/nitrosative stress levels, mediated by administration of peroxynitrate or H2O2 to neuroblastoma cells, lead to reduced BVR-A protein levels along with mTOR hyper-activation, as observed in BVR-A−/− mice." (PMID 32727065, 2020). "Indeed, both LY294002 and rapamycin significantly enhanced entinostat-mediated effects on cell viability, suggesting that HDAC1–3 inhibitors, but not HDAC8 inhibitors, cooperate with PI3K/mTOR inhibitors in our neuroblastoma MYCN-driven model." (PMID 29515255, 2018). "Initial studies have identified synergistic combinations of ALK inhibitors with mTOR inhibitors and with CDK4/6 inhibitors, and these combinations may serve to overcome some of the limitations of single-agent ALK inhibitor treatment for neuroblastoma." (PMID 30384486, 2018). "While mTOR inhibitors increased PGRN expression in some cell lines (HEK293T, H4, HeLa), they failed to raise PGRN in more neuronal cell types under the same treatment conditions, including neuroblastoma cells and primary mouse neurons, as well as human iPSC embryoid bodies." (PMID 27341800, 2016). "Unexpectedly, our studies demonstrate that neither mTOR nor GSK3 inhibitors disturb the expression of P2X7R in neuroblastoma cells, indicating that non-canonical downstream effectors of Akt, or even directly Akt, should be implicated in the transcriptional regulation of P2rx7 gene." (PMID 26687764, 2015). "Here, we found that OLE induces autophagy in cultured neuroblastoma cells by a mechanism substantially in accordance with those previously reported for other polyphenols, confirming that in cells treated with polyphenols the Ca2+/CaMKKβ/AMPK/mTOR axis is actually at work." (PMID 26474288, 2015). "Additionally, the combination of small molecule inhibitors of GLI and PI3K/mTOR signaling revealed no additive or synergistic effects on the suppression of neuroblastoma cell growth." (PMID 25134527, 2014).